CD24 (CD24 molecule)
Diseases named in the same sentence as CD24 in open-access papers (continued):
Sharing a sentence is not in itself a finding about the gene and the disease.
tumor (continued). "The primary tumor and the liver metastases of the mice burdening MDA-MB-231 cells were stained with antibodies targeting CD44, CD24 and ALDH1 and were imaged with fluorescent microscopy." (PMID 29062075, 2017). "Several studies revealed that malignant ascites-derived exosomes contain multiple cargos, such as L1CAM, CD24, ADAM10, Claudin-4 and EMMPRIN which play a critical role in tumour progression." (PMID 29100532, 2017). "Syndecan-1 (CD138), MUC-1 (CD227) CD45, CD34, and the putative cancer stem cell markers CD15, CD24, CD44, and CD133 surface expression were evaluated on CSF floating tumor cells." (PMID 28399903, 2017). "Isolated from solid biopsies and tumor cell lines, cancer stem cells are currently identified by surface antigen expression using a number of putative stem cell markers including CD15, CD24, CD44, and CD133." (PMID 28399903, 2017). "Next, multicolor flow cytometry was used to evaluate the percentage of cells that were positive for CD24, CD44, EpCAM, CD133, and their combinations in three tumor-derived cell lines." (PMID 27414409, 2016). "In the same study, it has been shown that deletion of CD24 reduced BBN-induced bladder carcinogenesis, and that tumor reduction effect was more striking in male than in female mice." (PMID 26862755, 2016). "In our studies, we demonstrated that CCL2 gene silencing in MDA-MB-231 tumor xenografts inhibited ALDH1 expression, and reduced the number of CD24-/CD44+ cells." (PMID 27283985, 2016). "This difference of the relative pool of CD24+CD90+ cells in 12 and 14 week MMTV-PyMT mice is likely due to the exponential tumor growth occurring in this cancer model between the age of 11 and 14 weeks." (PMID 27542270, 2016). "Cells co-expressing CD24 (epithelial marker) and CD44 (mesenchymal marker), CD24hi CD44hi, have been shown to correspond to a hybrid E/M phenotype and possess higher tumour-initiation potential in vitro and in vivo." (PMID 27170649, 2016). "Our results indicate that Cetuximab alone or in combination with Ixabepilone significantly inhibited tumor growth and reduced CD44+/CD24-/low CSC population in vitro and in vivo." (PMID 26757880, 2016). "Behavioral observation further depicted the critical roles of CD44 and CD24 in maintaining the CSC characteristics such as resistance to therapy, self-renewal capacity, tumor initiation capacity, and metastatic potential in NPC CSCs." (PMID 27521216, 2016). "In this study, GSI exposure diminished the subpopulation of CD24+CD44+ in all CC cell lines and induced a significant reduction of anchorage-independent growth and delayed tumor engraftment in mice." (PMID 27821106, 2016). "Altogether, Over-expression of CD90, CD24, CD13 and CD133 in HCC correlated with more aggressive tumor behaviors and worse clinical outcomes in HCC patients." (PMID 26735577, 2016). "We found in both cells and tumors a marked upregulation in CTFG and a significant reduction of SLP1 expression in the CD24+/IGF1R-KD; tumor-suppressor and tumor-promoting genes respectively." (PMID 27179633, 2016). "By isolating tumor cells from the implanted bone, we retrieved a cell population resembling the heterogeneity of the primary tumor, with about 10% of CD105+CD24− RCC stem cells." (PMID 27322553, 2016). "MEC cells of IFDUC1, derived from a tumor characterized as ER+/PR+/Her2+ and non-BRCA1 hereditary were both CD44+ and CD24+." (PMID 26968831, 2016). "For example, several studies have reported cytoplasmic localization of CD24 in PDAC as well as in other tumor types." (PMID 27414409, 2016). "In spheriod-forming assays using tumor cells derived from Apc1572T/+ mice, Lin-CD29+CD24+ tumor cells gave rise to significantly more spheroids than Lin-CD29+CD24- tumor cells, suggesting that CD24-expressing cells are enriched for stemness properties." (PMID 26978528, 2016).
tumor (continued). "We showed high expression of the examined CSC markers among all of the cell lines and tumor samples, with the exception of CD24 and CD44, which were enriched under in vitro conditions compared with tumor tissues." (PMID 27414409, 2016). "Here we report c-MET expression on CD105+ CD24− RCC stem cells which, implanted SC in NOD-SCID mice, recreate the heterogeneity of the primary tumor, including a subpopulation of RCC stem cells expressing CD105 and c-MET." (PMID 27322553, 2016). "These datas suggested that CD24 possiblely promoted the CRC metastasis by regulating the expression of VEGF, which was responsible for tumor MVD." (PMID 27494878, 2016). "To further address the correlation between CD24, CD44, and SSEA4 expression, we performed containing of these markers on residual tumor nodules after AC chemotherapy and on untreated tumors of three independent models." (PMID 26607327, 2015). "We found that CD24- cells lost their propensity to form spheres in SFM and that when grafted in NOD/SCID mice, their rate of tumour progression was >50% lower than that of their mock-transfected counterparts." (PMID 25932953, 2015). "To investigate the role of CSCs markers in TNBC cancerogenesis and tumor progression, we selected 160 TNBCs samples on which we detected protein expression of CD44, CD24, CD133, ALDH1, and ABCG2 by immunohistochemistry." (PMID 26504780, 2015). "Mesospheres, typified by the stemness markers CD24, ABCG2 and OCT4, initiated tumours in immunodeficient mice more efficiently than adherent cells." (PMID 25932953, 2015). "We also examined and confirmed that ESA+/CD24- cells have CSC properties compared to ESA-/CD24+ which sorted from MDA-MB-453 cells based on its high spheroid formation and in vivo tumor formation ability." (PMID 26338199, 2015). "Animals injected with PanD3 cells (containing 9.3% of CD95+, 17.8% CD24+ and 23.6% CD44+ cells) developed tumours that were manually detectable 3 months after the injection." (PMID 25613377, 2015). "To estimate the proportion of CD44high/CD24low cells, we characterized tumor-derived cell lines by flow cytometry for surface expression of CD44 and CD24, respectively." (PMID 25361000, 2014). "To confirm our immuno-histochemical analysis of CD44, CD24, CD34, CD117 and Oct4 positive cells in orthotopic tumors, we performed Western blot analysis of the tumor extracts using specific antibody for markers detected by immuno-histochemical staining." (PMID 25264898, 2014). "In contrast a significant increase in expression of CD24, CD34, CD44 and Oct4 was observed in tumor extracts from animals treated with CIS (6 mg/kg) as compared to mock-treated mice or mice treated with WFA (2 mg/kg) alone." (PMID 25264898, 2014). "To screen for other markers of cancer stem cells in PTs, we harvested the BC-P007 xenografted tumor cells for FACS sorting using a panel of markers including CD29, CD44, CD90, CD117, CD 133, CD166, GD2, CD10, CD24 and ALDH." (PMID 24670249, 2014). "When U-CH1 cells were maintained in hypoxia, we found an increase in the expression of notochord markers (T, CD24, FOXA1, ACAN and CA12), tumour-sphere formation and cell growth, and a decrease in cell migration." (PMID 25541962, 2014). "CD24 and CD44 expression levels were also analyzed according to age, sex, tumor differentiation, depth of invasion, lymph node metastasis, and TNM stage." (PMID 25212506, 2014). "Consistent with our findings in mice, Mo-MDSC increased the ALDH1Bright and CD24+, CD44+ CSC population in BxPC3 after coculture as compared to control tumor cells." (PMID 24652403, 2014). "TNBC tumors recurrence following treatment with PARP-inhibitors can be explained by recent studies demonstrating that PARP-inhibitors eliminate the bulk of tumor cells, but they have limited ability to eliminate CD44+/CD24− CSCs." (PMID 24970653, 2014).
tumor (continued). "In our study, when Bmi1 expression was silenced in the CD44+CD24+ESA+ pancreatic CSC population, both in vitro CSC propagation and in vivo tumor growth were significantly inhibited." (PMID 23437065, 2013). "Beside CD133, markers such as CD24, EpCAM, CD166, Lgr5, CD47, and ALDH have been discussed and serve for the selection of tumour-initiating cells." (PMID 23150174, 2013). "From 130 samples, 40 (30%) expressed this phenotype (CD44+/CD24-); of these, 37 were high-grade tumors (II and III) and lymph node metastases and only three samples were grade I neoplasms." (PMID 24119896, 2013). "WT MMC and relapsed MMC tumor cells were then analyzed for the expression of neu and the stem cell markers CD44 and CD24." (PMID 24324806, 2013). "The downregulation of CD24 reduces STAT and FAK activity, decreases cell proliferation, metastasis in human tumor, and reduces E-cadherin (E-cad) expression in cultured epithelial cells." (PMID 23970932, 2013). "Other study has found similar, but not identical, results since the authors compared neoplastic cells in lymph nodes metastases with their corresponding primary tumor and found that metastatic cells contained a higher frequency of CD44+/CD24- cells." (PMID 24119896, 2013). "Our results clearly implicate that CUR prevents CRC cell metastasis via inhibition of CD24 interaction with Sp-1 and FAK in CRC tumor cells." (PMID 23970932, 2013). "Moreoever, CD44+/CD24- cells showed a unique surface ultrastructure by SEM and had the highest tumorigenic potential in tumor cell invasion and nude mouse xenograft assays." (PMID 23799994, 2013). "It was reported that cell surface molecule such as CD24 mediates c-Src kinase for FAK phosphorylation and paxillin which in turn promote integrin-dependent adhesion and tumor cell invasion and metastasis." (PMID 23970932, 2013). "The CD24 mediates c-Src kinase for FAK phosphorylation and paxillin which in turn promote integrin-dependent adhesion and tumor cell invasion and metastasis." (PMID 23970932, 2013). "We obtained four subtypes of tumor cells (i.e., CD44+/CD24-/low, CD44+/CD24+, CD44-/CD24+, and CD44-/CD24-)." (PMID 23799994, 2013). "Because the cells located in the periphery and center of the tumor responded differently to docetaxel, CD44 and CD24 expression was analyzed in both regions." (PMID 23301003, 2013). "The highly differentiated C12 tumor type, and the C13 poorly differentiated tumor, demonstrate also a stable surface phenotype of CD44+/CD24+ and ALDH activity, which has been related to self-renewing CSC." (PMID 24358304, 2013). "We observed that a subpopulation of tumor cells in all the samples showed dual expression of EpCAM with CD44, CD24 and ABCG2 individually." (PMID 22328825, 2012). "We examined four parameters of CSC phenotype and function: CD24/44 levels, dye efflux, ALDH activity and tumor initiating frequency in xenograft models." (PMID 23144633, 2012). "The individual expression of CD44, CD24, ABCG2, and EpCAM in primary tumor samples ranged from 19% to 64%, 15% to 77%, 2% to 7%, 4% to 65%, respectively." (PMID 22328825, 2012). "Whereas only 0.01% of the bulk tumor cells were capable of seeding tumor growth in NOD/SCID mice, 0.5% of the CD44+CD24−/low: Lineage− fraction was able to engraft and give rise to tumors." (PMID 22470504, 2012). "Both ALDH expression and CD44 and CD24 expression were positively correlated with xenograft formation in NOD/SCID mice, with both populations being equally capable of tumor initiation." (PMID 24213498, 2012). "Our previous study also revealed that CD24 expression occurred in 92.5 % of human CRC tissue and increased with tumor progression." (PMID 22731636, 2012). "The co-expression of EpCAM+CD44+, EpCAM+CD24+, and EpCAM+ABCG2+ ranged from 0.83% to 42.6%, 0.65% to 41.4%, and 1.6% to 6.5%, respectively, in the eight RB tumor samples." (PMID 22328825, 2012).
tumor (continued). "Several kinases that also inhibited the tumor-initiating CD44high population in SUM149 after siRNA treatments were identified and tested directly against sorted CD44high/CD24-/low cells of SUM149." (PMID 22309939, 2012). "First, it was demonstrated that CD44+, CD24+ and ESA+ (EpCAM+) positive PDAC cancer cells show stem cell properties and enhanced tumor initiating capacity compared to bulk tumor cells." (PMID 23094026, 2012). "Several cell surface markers, including CD24, CD44, CD133, CD166, EpCAM, or dye efflux assays have been used to sort populations of putative cancer stem cells from primary tumor cultures or cell suspensions obtained from tumor biopsies." (PMID 21264259, 2011). "CD24 is overexpressed in aggressive HCC cell lines and in the tumor tissues of patients with recurrent HCC." (PMID 21676268, 2011). "CD44 and CD24 have previously been identified as pancreatic CSC markers and represent a very small percent of the population of all tumor cells (0.1%)." (PMID 21695188, 2011). "In Kaplan–Meier survival analyses, the patients with increased CD44+/CD24− and ALDH1+ tumour cell populations had a significantly shorter DFS times than the remaining patients (P=0.043 and 0.041, respectively)." (PMID 21559013, 2011). "Thus, the high CD24 level on tumor cells may predict poor prognosis in patients with cancer." (PMID 20950440, 2010). "Propagation of spheres from tumor tissue or directly from the cell line enriched for ALDH activity and CD44+/CD24- markers and expression of EMT markers as well as genes that promote stem cell survival." (PMID 20615238, 2010). "Along with traditional markers such as FABP5, epidermal growth factor receptor, E-cadherin, CD74, and CD24, newly published biomarkers for the staining of HNSCC primary tumor biopsies include IL13Rα2, CD44v6, and the stem cell marker CD133." (PMID 20175927, 2010). "As compared to the CD44+CD24+ CSC subpopulation, ALDH+CD44+CD24+ CSCs showed stronger tumor-initiating capacity, a significant mesenchymal gene profile and higher correlation to metastasis." (PMID 24281178, 2010). "After 4 weeks, the analysis of luciferase activity indicated that cells in the CD24−/low/CD44+ populations of HCC1954-Luc and MCF7-Luc generated significantly larger tumours than the control populations (P<0.05)." (PMID 19997106, 2010). "Five potential novel target genes (FABP5, CD24, CD44, CD74, and HSP27) were identified, which were highly expressed in HNSCC tumor samples and tissue arrays." (PMID 19602232, 2009). "Future studies will focus on the isolation and characterization of the CD24+/CD44+ and other marker positive tumor subpopulations from HNSCC." (PMID 19602232, 2009). "Tumor cells were distinguishable from stromal cells and inflammatory cells (generally CD44+ and CD24-) by expression of cytokeratin clone AE1/AE3 in adjacent sections." (PMID 18559090, 2008). "As anchorage-independent growth is an approximation of tumorigenesis and cancer stem cells are thought to be the tumour-initiating cells, we tested the ability of LNCaP CD44+CD24− cells and CD44+CD24−-depleted cells to form colonies in soft agar." (PMID 18268494, 2008). "Thirteen percent (30/240) of the tumors were positive for more than one of the CD44+/CD24-, CD44-/CD24+ and CD44+/CD24+ phenotypes, with 5% (11/240) displaying tumor cells of all three phenotypes." (PMID 18559090, 2008). "Tumours excised from mice injected with either 1000 CD44+CD24− cells or 5 million total LNCaP cells were dissociated, and expression patterns of CD44 and CD24 were analysed by flow cytometry." (PMID 18268494, 2008). "To validate differential expression of two candidate markers at the protein level, we performed immunohistochemistry to detect CD24 antigen and SPARCL-1 protein in a pair of slides representing a benign and malignant tumour." (PMID 16969345, 2006). "In this analysis, we included tumour grading (G1 and G2 vs G3), disease stage (I–II vs III–IV) and CD24 expression (0, 1+ vs 2+, 3+)." (PMID 12610508, 2003).
tumor (continued). "Elevated levels of sialylation in tumor cells can enhance the presentation of sialylated ligands such as Mucin proteins (e.g., MUC1), CD24, and sialylated IgG on the cell surface, further facilitating their interactions with specific receptors known as Siglecs38-41." (PMID 41584035, 2026). "Consistently, flow cytometric analysis using established surface markers CD24 and CD133 revealed that STK38 upregulation significantly increased the proportion of CD133+CD24+ double-positive cells in Caki-2 and ACHN cells, supporting its role in sustaining self-renewing tumor phenotypes." (PMID 41540036, 2026). "Although the tumor burden of VA and CD24 clones of MOC-L1 were not different, CD24 clones had a higher volume of spleen relative to VA controls." (PMID 41585138, 2026). "Tumor cells could use the “Don’t eat me” signal, such as CD47 34, SIRPG PD-136 and CD24 37, to escape recognition and phagocytosis by macrophages, which were significant contributors to the recurrence, metastasis, and therapeutic resistance of various cancers." (PMID 40682115, 2025). "CD24+CD271+ staining is therefore not specific to tumours that are BRAF/NRAS wildtype, nor to BRAF/NRAS mutant tumours." (PMID 40754577, 2025). "CD24 was uniformly expressed, while CD44 levels varied across PF and tumor-derived cells." (PMID 40877861, 2025). "There was no data on CD44/CD24 expression in TNBC patients with special attention to tumor stroma nor in the entire tumor area." (PMID 39904885, 2025). "Unlike CD47, CD24 has a more restricted distribution in healthy tissues and higher expression in tumor tissues." (PMID 41354057, 2025). "have recently identified CD24, a glycosylphosphatidylinositol (GPI)-anchored protein, as a novel ‘don’t eat me’ signal expressed on tumor cells to evade macrophage-mediated phagocytosis by binding to Siglec10 inhibitory receptor expressed on tumour-associated macrophages." (PMID 39996058, 2025). "While CD24 expression can be induced in some senescent contexts, it paradoxically also plays a role in enabling certain cancer cells to evade senescence or modulate the SASP, thereby influencing the tumor microenvironment." (PMID 40777020, 2025). "Additionally, tumor cells can express “don’t eat me” signaling proteins on the cell membrane, such as CD47 and CD24, to avoid macrophage phagocytosis and thus escape immune response." (PMID 40814015, 2025). "In our analysis, we observed that the chemo-naïve basal tumor samples had high CD44 and low CD24 expression (CD44+/CD24−/low phenotype), which could be interpreted as BCSC-enriched, consistent with previous studies on chemoresistant cohorts." (PMID 40362201, 2025). "Notably, CD24 is overexpressed in HCC, where its expression correlates with increased tumor invasiveness, metastatic potential, enhanced proliferation, and activation of the Wnt/β-catenin signaling pathway." (PMID 40830893, 2025). "In mouse xenografts, RCC2 KO increased lung metastasis without significantly affecting primary tumor growth, while CD24 KO reduced both tumor growth and metastasis." (PMID 41090358, 2025). "However, to evade clearance, tumor cells usually overexpress anti-phagocytic membrane proteins with “don’t eat me” signals, such as CD47, CD24, MHC-I, and PD-L1." (PMID 40873588, 2025). "Using our in-house cohort, we evaluated CD24 mRNA expression in HCC tumor and paired adjacent nontumor tissues." (PMID 40830893, 2025). "Among the tumor antigens that have been investigated in preclinical studies and partly in clinical studies, several highly glycosylated proteins, such as mesothelin, mucin 1, CA125 or CD24, have been identified." (PMID 39432076, 2024). "used CD24/Siglec-10 blocking peptide (CSBP), which blocks the interaction between CD24/Siglec-10 and PD-1/PD-L1, to enhance macrophage-mediated phagocytosis of tumor cells and activate CD8 T cells." (PMID 39351237, 2024).